IL25 (interleukin 25)
Diseases named in the same sentence as IL25 in open-access papers (continued):
Sharing a sentence is not in itself a finding about the gene and the disease.
asthma (continued). "Recently, several studies showed that epithelium-derived cytokines, namely IL-25, IL-33, and TSLP, act as key regulatory factors in immune-pathogenic mechanisms of allergic rhinitis, asthma, and CRSwNP mainly involved in type 2 inflammatory responses." (PMID 35162939, 2022). "HDM-specific immunoglobulins in serum are positively correlated with IL-25 expression, and IL-25 involved in the development of atopic dermatitis, allergic rhinitis, and asthma sensitized to HDM." (PMID 36119076, 2022). "We also assessed RV-induced IFN protein expression at 4 d p.i. in n = 7 ALI-BECs (moderate to severe asthma) treated with LNR2 (isotype control) or LNR125 IL-25 neutralising antibody." (PMID 35508632, 2022). "It is commonly thought that epithelial-derived alarmins (IL-33, TSLP, IL-25) play an upstream role in the pathogenesis of asthma where basophil-derived cytokines are a pivotal component of allergic inflammation." (PMID 35693823, 2022). "The release of IL-25 from epithelial cells in asthma also leads to overproduction of IL-4, IL-5, IL-9, IL-13, and CCL11, which then initiate recruitment of eosinophils, DCs, ILC2s, basophils, T cells, and other immune cells." (PMID 36311787, 2022). "Collectively, it is evident that from their prime position in the inflammatory cascade, TSLP, IL-25 and IL-33 orchestrate the elicitation and activity of multiple effector cells and pathways that constitute the asthma phenotype." (PMID 36311787, 2022). "Meantime, after the RSV challenge, administration of anti-IL-25 antibody in mice prevents some pivotal features of asthma." (PMID 36119076, 2022). "In models of asthma and parasitic infections, blocking any of IL-25, IL-33, or TSLP alone showed only modest results, while combinatorial targeting of IL-33, IL-25 and TSLP significantly reduced collagen expression and fibrosis." (PMID 38566909, 2022). "Allergens, toxic substances, and viral infections cause the release of IL-25, IL-33, TSLP cytokines, the so-called alarmins, from the airway epithelium and induce type-2 inflammation via ILC2 and Th2 cells in asthma." (PMID 36326393, 2022). "The focus of this study was to understand the effect of IL-25 on anti-viral immunity in asthma to determine the therapeutic potential of IL-25 blockade for viral asthma exacerbations." (PMID 35508632, 2022). "It is currently believed a similar type of IL-25 positive chemosensory cell exist in the human nasal cavity which would increase the relevance of IL-25 in asthma even further." (PMID 36311787, 2022). "The induction of IL-25 by rhinoviruses in lung epithelial cells and concomitant activation of T2 inflammation was distinctly higher in samples from asthma patients." (PMID 36311787, 2022). "The contribution of IL-25 on asthma symptoms by its direct action on lung endothelial cells, DCs, and Th2 cells has been well documented." (PMID 35615348, 2022). "It has been clarified that IL-25 acts on the progression of asthma and has been considered as a biomarker for the prognosis." (PMID 36119076, 2022). "IL-25 and its receptor are expressed in airway epithelial cells of healthy individuals and patients with asthma and antibody-mediated blockade of IL-25 enhances antiviral immunity and blocks virus-exacerbated asthma responses." (PMID 35508632, 2022). "Epithelial-derived cytokines [i.e., TSLP, IL-33, IL-25] act as upstream cytokines in asthma pathobiology." (PMID 36359917, 2022). "IL-25 signaling is proposed to be involved in infection, asthma and allergy, psoriasis, autoimmunity including inflammatory bowel disease (IBD), rheumatoid arthritis, multiple sclerosis, Sjögren’s Syndrome and cancer." (PMID 36263033, 2022). "The mechanisms through which IL-33 and IL-25 differentially counter anti-viral responses suggest that alarmin cytokines can promote asthma severity culminating from various viral infections, which can be harnessed as treatment strategies." (PMID 36311787, 2022).
asthma (continued). "In BECs from donors with asthma, this was through inhibiting the suppressive effects of IL-25 on IFN production and ISG expression and reducing type-2 inflammation." (PMID 35508632, 2022). "The structural features of the IL-17R tip-to-tip interactions are compatible with small-molecule targeting, for example, to inhibit aberrant IL-25 signalling in asthma or psoriasis." (PMID 35863378, 2022). "Epithelial-derived alarmins (IL-33, TSLP, and IL-25) play an upstream role in the pathogenesis of asthma." (PMID 35693823, 2022). "In asthma, the role of IL-25 appears to be primarily recognised as a detriment to positive health outcomes." (PMID 36311787, 2022). "While prospects are promising for prevention of TSLP-mediated inflammation through tezepelumab, therapies against the other two alarmins, IL-25 and IL-33 are currently lagging as effective treatments in asthma." (PMID 36311787, 2022). "Asthma is a type 2-mediated inflammatory disease, and the alarmins interleukin-25 (IL-25) and interleukin-33 (IL-33) play essential roles in shaping the Th2 response signature found in asthma." (PMID 35444658, 2022). "In asthma mouse model, IL-25-/- mice were exposed to HDM to investigate the effect of IL-25 on eosinophils during the sensitization phase." (PMID 35615348, 2022). "We noted abundant constitutive expression of IL-25 protein at the apical surface airway epithelial cells from both healthy donors and subjects with asthma." (PMID 35508632, 2022). "One insight from the IL-25 blockade transcriptomic data in BECs from donors with asthma highlighted that IL-25 regulates TGF-β signalling; a contributor to airway remodelling." (PMID 35508632, 2022). "Deregulation of IL-25 has been found in many inflammation-related diseases, including helminth parasite infection, inflammatory bowel disease, asthma, severe hepatitis, and NAFLD." (PMID 36119529, 2022). "Epithelial cell-expressed IL-25 promotes allergic diseases such as asthma and is increased during viral asthma exacerbations." (PMID 35508632, 2022). "IL-25 is highly expressed in the murine model of asthma established by ovalbumin (OVA) or house dust mite." (PMID 36119076, 2022). "In a previous study where serum levels of 24 different cytokines and chemokines were studied in severe asthmatic patients, IL-25 levels were also similar in control and asthma groups." (PMID 36326393, 2022). "IL-33 biologics have shown limited progress in exploring their use for asthma treatment, despite having been tested in more clinical trials than those of IL-25." (PMID 36311787, 2022). "Immune transcriptome analysis of LNR125 treated BECs from individuals with asthma indicated that blocking IL-25 restored antiviral immunity with evidence of upregulation of ISGs, such as IRF7 and TBK1 and interleukin-1 receptor-associated kinase 2 (IRAK2)." (PMID 35508632, 2022). "We next investigated the effect of LNR125 treatment on IL-25 signalling in n = 9 ALI-BECs derived from patients with moderate to severe asthma." (PMID 35508632, 2022). "Together these observations strongly support IL-25 as a critical factor for allergic responses, and that IL-25 blockade has the potential to alleviate asthma and allergic inflammation." (PMID 35406669, 2022). "Here we used human endobronchial biopsies and differentiated primary human BECs (healthy donors and patients with asthma) to gain insight into coexpression of IL-25 and IL-17RB by differentiated BECs." (PMID 35508632, 2022). "In human asthma, we previously reported that epithelial IL25 mRNA expression was upregulated in a subset of asthma patients featured by type 2 inflammation." (PMID 33945508, 2021). "In chronic rhinosinusitis with nasal polyps (CRSwNP), a disease related to asthma, various expression patterns of IL-25, IL-33, and TSLP in different populations and regions have been described." (PMID 33945508, 2021).
asthma (continued). "An RV-induced asthma animal model revealed an increased intrinsic capacity for type 2 cytokines in the lung, and IL-25 is a key mediator of RV-induced exacerbation of pulmonary inflammation, especially in early life." (PMID 35008429, 2021). "Alarmins such as thymic stromal lymphopoietin (TSLP), IL-25 and IL-33 can drive allergic inflammation in response to airway damage and their expression correlates with asthma severity." (PMID 34777398, 2021). "Alarmins are innate cytokines, including thymic stromal lymphopoietin (TSLP), interleukin-33 (IL-33), and interleukin-25 (IL-25), which are mainly produced by airway epithelium and exert a prominent role in asthma pathobiology." (PMID 34572294, 2021). "TSLP, IL-25 and IL-33 are involved in the pathophysiology of allergic diseases, including asthma and atopic dermatitis, as they activate the Th2-dependent immune response." (PMID 34301307, 2021). "IL-25 emerged as a key determinant of virally induced asthma exacerbations, in fact it has been demonstrated that viral infections of the airway epithelium resulted in increased release of IL-25 in asthmatic patients." (PMID 34608100, 2021). "In a murine model of HDM asthma, IL-25 directly stimulated Th2/Th9 cells to produce IL-13 and IL-9, and the role of CD11c+ DCs was important in that their stimulation with IL-25 promoted the local accumulation of the T cells." (PMID 35387007, 2021). "In a mouse model of asthma, manipulation of airway miR-206 expression altered IL-25, IL-33, and Tslp expression; ILC2 expansion; and type 2 airway inflammation." (PMID 33945508, 2021). "It has been reported that transgenic mice with IL-25 overexpression in pulmonary epithelial cells spontaneously develop asthma-like symptoms, including mucus production and airway infiltration by macrophages and eosinophils." (PMID 34122457, 2021). "As an adaptor protein in the downstream of IL-17 cytokine family, Act1 controls the allergic asthma-like inflammation initiated by IL-25 while depletion of Act1 abolishes the asthma symptom in mice." (PMID 34122457, 2021). "It is worth noticing that IL-17RA together with IL-17RB is an important part of IL-25 signaling—an epithelial derived alarmin significant in asthma pathobiology." (PMID 32842623, 2020). "Thymic stromal lymphopoietin (TSLP), IL-33, and IL-25 are three epithelial-derived cytokines with critical roles in asthma pathogenesis as they are potent activators of DCs and ILC2s, which act upstream in the T2 immune response cascade." (PMID 33255348, 2020). "Previously, it was found that in murine, the Th17 cells also play an important role at the asthma pathogenesis by producing IL-17, IL-23, IL-25, which results in airway inflammation." (PMID 32155894, 2020). "Overwhelming evidence supports a central role for the three epithelial-derived cytokines, TSLP, IL-33, and IL-25, in asthma." (PMID 33255348, 2020). "Yet, emerging evidence suggests the involvement of the T2-promoting cytokines IL-25, IL-33, and TSLP in the response to respiratory viruses and associated exacerbations in asthma." (PMID 33255348, 2020). "More recently, bronchial epithelial cells from patients with asthma have been shown to express IL-25 in response to RV, and this can enhance Th2 inflammation." (PMID 32637363, 2020). "Group 1 consists of an anti-TSLP antibody, anti-IL-33R antibody, anti-IL-33R antibody, anti-IL-25 antibody, and anti-IL-6 antibody, which are investigational drugs for asthma." (PMID 31284537, 2019). "It is found that the amount of IL-25 in the sputum was correlated with the severity of asthma—the highest level of IL-25 in sputum was found in severe asthma." (PMID 31885750, 2019). "For example, IL-25 augments type 2 immune responses and promote the airway inflammation of patients with asthma." (PMID 31481966, 2019). "We previously reported that IL-25 is crucial for development of allergic contact dermatitis as well as asthma in mice." (PMID 31745167, 2019).
asthma (continued). "The deregulation of IL-25 has been found in many inflammation-related diseases, including helminthes parasitic infections, inflammatory bowel disease, asthma, fulminant hepatitis, and NAFLD." (PMID 31296243, 2019). "In particular, airway concentration of IL-17 and its related cytokines (IL-17A and IL-25) are upregulated in patients with uncontrolled asthma; their levels have been positively correlated to neutrophilic inflammation and asthma severity." (PMID 31355170, 2019). "Specific immunotherapy reduced asthmatic Th2 cytokine levels and the production of IL-25 and alleviated oxidative stress and cell apoptosis in the lung tissue of an asthma mouse model." (PMID 30345318, 2018). "In summary, IL-25 high affinity receptor part (IL-17RB) expression on EoP is increased in the peripheral blood of subjects with asthma after allergen challenge." (PMID 29456832, 2018). "Primary BECs from patients with asthma have increased expression of IL-25, which correlates with the donor atopic status." (PMID 30345002, 2018). "The current study suggests that IL-25 plays a role in the recruitment of immature eosinophils to the airways in asthma." (PMID 29456832, 2018). "Expression of IL-25 has been reported to be increased in epithelial cells from patients with asthma and can be induced further by rhinovirus infections." (PMID 28583446, 2017). "ILC2 have been implicated in asthma, since ILC2 produce large amounts of IL-5 and IL-13, as well as IL-4 under certain context, in response to IL-33, IL-25, and TSLP." (PMID 29354125, 2017). "There was a strong expression of TSLP, IL-25, and IL-33 in the epithelium, the endothelium of small vessels and subepithelial infiltrating cells in the nasal tissue derived from severe asthma patients with CRS (respectively)." (PMID 28199345, 2017). "Though IL-25 appears to serve a similar function to IL-33, experimental mouse models of asthma have elucidated some important differences." (PMID 28959799, 2017). "Here, we further studied the impact of Shp2 on the expression of epithelium-derived cytokine IL-25, which was important in type 2 immune response in asthma." (PMID 28481957, 2017). "Although there is increasing knowledge about the function of IL-25 in asthma, the mechanism for how IL-25 is produced is still poorly studied." (PMID 28481957, 2017). "Studies demonstrated that omentin was involved in allergen-induced IL-25 and IL-33 production in asthma." (PMID 29283409, 2017). "Higher expression of Th2-driven cytokines (IL-4, IL-5, IL-9, and IL-13), TSLP, IL-25 and IL-33 in nasal tissues was observed in severe asthma." (PMID 28199345, 2017). "During the inflammatory process of asthma, multiple cytokines are secreted by alveolar epithelial cells, such as IL-25 (IL-17E), TSLP, and IL-33, that can initiate and modulate a Th2-like immune response." (PMID 28800119, 2017). "Previous reports have shown that IL-25 expressed hyper-reactivity in an experimental mouse-model of asthma." (PMID 27617447, 2016). "Mice exposed to OVA in both groups (asthma and anti-IL-25) demonstrated a significant increase in the number of total cells (P< 0.05) and eosinophils (P< 0.05), particularly compared with those of the other groups." (PMID 27617447, 2016). "Roles of the cytokines IL-33, thymic stromal lymphopoietin (TSLP) and IL-25 in asthma are receiving considerable interest." (PMID 26879906, 2016). "Interleukin-25 (IL-25) is a potent activator of type-2 immune responses, and is responsible for airway inflammation in asthma." (PMID 27617447, 2016). "Three bronchial epithelial upstream cytokines; IL-33, TSLP and IL-25 are considered to trigger type-2 inflammation in asthma." (PMID 26879906, 2016). "To further confirm the expression pattern of the IL-25 gene in the OVA-induced asthma mice, we detected the gene’s expressions in the mRNA by means of quantitative real-time PCR, and in the protein by western blot, respectively." (PMID 27617447, 2016).
asthma (continued). "Th2-mediated immune response has been reported to play a crucial role in the pathophysiology of asthma through the induction of Th2 type cytokine production, by means of IL-25." (PMID 27617447, 2016). "Our data show that all of these pro-angiogenic agents have the potential to be upregulated by IL-25 alone in the setting of asthma-like inflammation of the airways in vivo, with a time course congruent with that of angiogenesis." (PMID 25889697, 2015). "IL-25, IL-33 and TSLP have been associated with asthma in a number of investigations, both in the clinic and in animal models, and reduction in their levels should have an important influence on AHR and airway inflammation." (PMID 26214807, 2015). "Secondly, we showed that chronic intranasal instillation of IL-25 into murine airways is able to induce acute and chronic inflammatory responses reminiscent of human asthma." (PMID 25889697, 2015). "IL-25 is also upregulated in asthma and has been shown to play a role in airway remodeling and angiogenesis both in vitro and in in vivo models." (PMID 26635811, 2015). "As IL-25 is often mentioned to be related to asthma like symptoms we reviewed IgE data to inhalant allergens." (PMID 24295226, 2013). "In this section, we review the significant roles of IL-25 and IL-33 and their main responder cells, ILCs2, in airway allergic diseases and asthma." (PMID 23209480, 2012). "Several studies indicated ILCs2 in allergic reactions and asthma as major responders to IL-25 and IL-33 and significant inducers of type 2 responses." (PMID 23209480, 2012). "Another aspect that should be considered is whether IL-25 could become a therapeutic target or biomarker in asthma." (PMID 40723867, 2025). "IL-25 is one of the major cytokines responsible for airway remodeling in asthma." (PMID 39962262, 2025). "In asthma, IL-25 is elevated, particularly during rhinovirus-triggered exacerbations." (PMID 41169790, 2025). "IL-25 has been investigated in the context of asthma quite extensively." (PMID 40723867, 2025). "IL-25 plays a crucial role in virus-induced asthma exacerbations." (PMID 41303221, 2025). "The promising efficiency of SM17 targeting IL-25 has been reported in pre-clinical studies both in asthma and AD, which could be a hopeful biologic for asthma and AD, even asthma combined AD." (PMID 40236701, 2025). "A similar pattern was observed in the expression profiles of throat Ck8+ epithelial cells in patient samples, with significant increases in TSLP and IL-25 when comparing GINA 5 to all other asthma patients (p < 0.001 and p = 0.003, respectively, after adjusting for age and sex)." (PMID 38999286, 2024). "Overall, IL-25 activation results in eosinophilia, in part by delaying eosinophil apoptosis, and therefore contributes to eosinophil-driven inflammatory diseases, such as asthma." (PMID 39717777, 2024). "IL-25 also contributes to structural changes in the airway by inducing collagen secretion by and the proliferation of fibroblasts, contributing to airway remodeling and hyper-responsiveness in asthma." (PMID 38999286, 2024). "Similarly, the activation of TLR4 by cockroach allergens results in the release of TSLP, IL-25, and IL-33, further contributing to the inflammatory environment characteristic of asthma." (PMID 39457624, 2024). "As IL-25 contributes to the pathology of asthma, blockade of its receptor by SM17 may serve as a promising approach to treat this disease." (PMID 39717777, 2024). "The expression of TSLP and, to a lesser extent, IL-25 is increased in patients with severe asthma." (PMID 38999286, 2024). "Moreover, blocking IL-25 via sIL-25R prevents experimental asthma in mice by inhibiting the development of AHR, allergen-specific IgE production, allergic airway inflammation, and increased mucus production." (PMID 38879568, 2024).